IL33 (interleukin 33)
Diseases named in the same sentence as IL33 in open-access papers (continued):
Sharing a sentence is not in itself a finding about the gene and the disease.
glioma (continued). "However, how IL-33 regulates EMT and stemness of glioma need to be further investigated." (PMID 32003751, 2020). "We speculated that glioma cells may release high level IL-33 that resulted in the stimulation of exogenous IL-33 for proliferation was not significant." (PMID 32003751, 2020). "Moreover, IL-33 treatment can contribute to TNC expression and promote glioma invasion." (PMID 31889095, 2019). "Tyrosine-specific phosphoproteomic analysis of IL-33+ tumors showed an increase in a number of phospho-peptides derived from STAT3, CDK1, CDK2, FYN, MAPK14, and MAPK3, some that based on amino acid sequence could be attributed to either human glioma or mouse host origin." (PMID 33020472, 2020). "Moreover, although the tumor burden was substantially increased in the IL-33-expressing glioma compared to the IL-33-negative tumors, the actual size of the tumor suggests that the clinical criteria for endpoint were not reached exclusively due to tumor burden." (PMID 33020472, 2020). "However, the exact role and mechanism of IL-33 in glioma are not clear." (PMID 31889095, 2019). "However, TNC was not significantly involved in IL-33-stimulated glioma migration." (PMID 31889095, 2019). "In this study, we examined the role of IL-33 and its receptor ST2 in nonmalignant cells in the glioma microenvironment." (PMID 39931535, 2025). "We analyzed the role of IL-33 and its receptor ST2 in nonmalignant cells of the glioma microenvironment and found that IL-33 levels are increased in cells surrounding the tumor." (PMID 39931535, 2025). "Interleukin-33 (IL-33) and its receptor ST2 have emerged as regulators of glioma growth, but their exact function in tumorigenesis has not been deciphered." (PMID 39931535, 2025). "CM from the IL-33+ cells resulted in an increase in migration and proliferation of the BMDM, a result in contrast to CM from glioma cells that did not express IL-33." (PMID 33020472, 2020). "Although we proved the role of IL-33 in promoting stemness and EMT, we did not observe a significant effect on glioma proliferation in vitro." (PMID 32003751, 2020). "In addition, RNA-seq and western blot analysis of the glioma cells show little or no detectable expression of ST2 further supporting that the secretion of IL-33 by the glioma cells is acting on other components of the tumor microenvironment." (PMID 33020472, 2020). "Importantly, a subset of these human-derived cytokines that included CXCL10, IL-33, CXCL8, KITLG, CCL2, and TGFα were not secreted or secreted at very low levels in vitro by BT147 cells, suggesting that the increased secretion was the result of a glioma–host cell interaction within the brain." (PMID 33020472, 2020).
Autoimmunity (31 papers, 2012 to 2025). The occurrence of an immune reaction against the organism's own cells or tissues. "The genetic polymorphism rs1929992 of IL-33 has been linked to various autoimmune conditions, reinforcing its role in the pathogenesis of CSU." (PMID 39769469, 2024). "Interleukin-33 (IL-33), a critical modulator in adaptive and innate immune, has been implicated in autoimmunity and inflammation." (PMID 28423665, 2017). "Elevated IL-33 in saliva could cause autoimmunity-related microbial dysbiosis." (PMID 36362030, 2022). "The instability of tissue Tregs, their conversion into proinflammatory ex-Tregs, and the loss of key homeostatic signals (e.g., IL-2, IL-33, and AREG) are common threads across autoimmune pathologies." (PMID 40933988, 2025). "The dual role of IL-33 is also reflected in the immune system, which promotes autoimmunity and anti-autoimmunity." (PMID 39925809, 2025). "More recently, cultured MCs derived from bone marrow, stimulated by specific ovalbumin and IgE, induced the expression and release of IL-33, which has an autocrine action on the expression of IL-6 and IL-13, cytokines also important in autoimmunity." (PMID 36362030, 2022). "Extracellular IL-33 augments immune responses during tissue inflammation and injury; however, its precise role in autoimmunity remains elusive." (PMID 34554930, 2021). "Treatment with OA also reduced the indices of inflammation and autoimmunity in colon tissues, (i.e., increased TNFα, IL-1β, IL-23, IL-17A, and KC; and reduced IL-13, IL-33, and IL-25)." (PMID 33246492, 2020). "Marked effects of excess soluble IL-33 in mice are indicated by lethal inflammation and autoimmunity in transgenic mice with high levels of soluble IL-33 bioavailability." (PMID 27703303, 2016). "Importantly, heart inflammation of multiple etiologies and Th skewness, such as ischemia and autoimmunity, activates a fibroblast-IL-33-ILC axis, which induces activation and differentiation of ILC2s." (PMID 30984196, 2019). "These subpopulations are phenotypically distinct: Th17 cells that mediate autoimmunity are characterized by high levels of IL-23R, IL-33 and T-bet expression when compared to their non-pathogenic counterparts that express elevated levels of IL-10." (PMID 23844143, 2013). "Interestingly, IVIG treatment was shown to suppress autoimmunity through IL-33 induced TH2 responses, suggesting that IL-33/ST2 pathway may activate anti-inflammatory mechanisms in other settings." (PMID 35069220, 2021). "A variety of circumstances like environmental stressors and mechanical damage to cells can results in necrosis and the release of IL-33 along with other nuclear components could activate the local immune system to initiate processes that can result in autoimmunity." (PMID 30574145, 2018). "Moreover, IL-33 may confer autoimmunity by augmenting innate immune responses." (PMID 34554930, 2021). "The IL-33/ST2 signaling pathway is an intercellular signaling system that is a factor in fibrosis, antigen–allergen response, and autoimmunity." (PMID 28881679, 2017). "sST2 acts as a decoy receptor that prevents the interaction of ST2L with IL-33, whereas ST2L binding its ligand IL-33 activates inflammatory responses in autoimmunity." (PMID 28415811, 2017). "It must be noted that the conflicting role of IL-33 as reported in pre-clinical models of IBD extends beyond the gut and IL-33 has been found to have both protective and exacerbating effects in systemic models of autoimmunity including EAE." (PMID 31231388, 2019).
endometriosis (31 papers, 2013 to 2025). The growth of functional endometrial tissue in anatomic sites outside the uterine body. "Our paper suggests that endometriosis, a leading cause of infertility, is linked to endometrial dysbiosis and two key cytokines, IL-17 and IL-33, which interact with intestinal dysbiosis." (PMID 39596052, 2024). "IL-1 receptor accessory protein (IL-1RAcP) plays a role in signaling IL-1 family cytokines, including IL-1, IL-33, and IL-36, which are implicated in chronic inflammatory diseases, autoimmune diseases, endometriosis, type 1 diabetes, and preeclampsia." (PMID 38337827, 2024). "Previous studies have demonstrated that IL-33 plays an essential role in several pregnancy-related diseases, including endometriosis, recurrent pregnancy loss and preeclampsia, etc.." (PMID 37403020, 2023). "Plasma and peritoneal fluid levels of IL-33 have been positively associated with deep endometriosis." (PMID 36428461, 2022). "Immunological markers including IL-33 and IL-17 and their associated pathways are key players in establishing a link between endometriosis and CVD." (PMID 34754275, 2021). "Here, we show that IL-33 significantly perpetuated local peritoneal inflammation, which is a key hallmark of endometriosis." (PMID 34699382, 2021). "Elevated serum IL-33 was associated with the intensity of painful preoperative symptoms and the extent and severity of the deeply infiltrating endometriosis." (PMID 33013364, 2020). "In a syngeneic mouse model of endometriosis, IL-33 injections caused systemic inflammation, which manifested as an increase in plasma pro-inflammatory cytokines compared to control mice." (PMID 29263351, 2017). "Research into IL33 gene polymorphisms in endometriosis patients may help clarify their role in cytokine regulation and disease severity." (PMID 39767772, 2024). "Notably, IL-33 elevation is implicated in endometriosis and exogenous IL-33 exacerbates lesion severity and fibrosis dependent on ILC2s in a murine endometriosis model." (PMID 35359972, 2022). "A large-scale genome-wide association study has identified a statistically significant single nucleotide polymorphism in the region of the IL-33 gene, suggesting that IL-33 dysfunction in endometriosis may be genetic in origin." (PMID 34699382, 2021). "The present study is aimed at finding out the association of inflammatory markers (C-reactive protein, fibrinogen, and homocysteine), proinflammatory cytokines (interleukin-17 and interleukin-33), and cardiovascular risk manifestation in females with endometriosis in comparison with the control." (PMID 34754275, 2021). "IL-33 plays a crucial role in the pathophysiology of various diseased conditions including fibrosis, inflammation, hypernociception, and vascularization, and all of these are also associated with the pathogenesis of endometriosis." (PMID 34754275, 2021). "Although plasma and peritoneal fluid levels of IL-33 have been associated with deep infiltrating endometriosis, its contribution to the disease pathophysiology is unknown." (PMID 29263351, 2017). "Therefore, elevated levels of IL-33 are associated with severe endometriosis pathology, and IL-33 has been suggested as a promising therapeutic target; however, the molecular mechanisms and associated immune cells that underpin how IL-33 contributes to endometriosis are not understood." (PMID 34699382, 2021). "In endometriosis, IL-33/ST2 inhibits ATF3 by activating the p38/JNK signaling pathway, thereby upregulating the expression of SLC7A11, reducing ferroptosis, and protecting endometriotic stromal cells (eESCs) from damage." (PMID 41550926, 2025). "In a more recent study, it was shown that the IL33‐IL33receptor (ST2) axis promotes epithelial–mesenchymal transition in endometriosis via β‐catenin phosphorylation." (PMID 40658772, 2025).
endometriosis (continued). "In the same study, an allograft mouse model of endometriosis showed that IL‐33 promotes fibrosis and increases the number of lesions, whereas blocking IL‐33 or ST2 decreases the number of lesions." (PMID 40658772, 2025). "This is because various proinflammatory cytokines, such as IL-17 and IL-33, are also found in both endometriosis and cardio-vascular diseases." (PMID 38337827, 2024). "Proinflammatory cytokines, including IL such as IL-1, IL-8, IL-33, nuclear factor kappa B (NF-κB), and TNFα, have been widely documented during various stages of endometriosis progression." (PMID 38540637, 2024). "Many different mechanisms can explain gut dysbiosis and endometriosis but can also propose a role for IL-17 and IL-33." (PMID 39596052, 2024). "Many inflammatory factors, such as tumor necrosis factor (TNF)-alpha, interleukin (IL)-1beta, IL-33 and IL-6, were upregulated in peritoneal fluid of women with endometriosis." (PMID 38961373, 2024). "In endometrium, IL-33 perpetuated inflammation, angiogenesis, and lesion proliferation, which are critical events in the progression of endometriosis." (PMID 39596052, 2024). "This increased IL-33 can be detected in the peripheral blood and peritoneal fluid of endometriosis patients." (PMID 39767772, 2024). "Nevertheless, IL-33 has been studied in other reproductive disorders including endometriosis and polycystic ovarian syndrome (PCOS)." (PMID 39713054, 2024). "Their results showed that IL-33 levels were increased in both the plasma and peritoneal fluid of patients with severe endometriosis compared with healthy controls." (PMID 39713054, 2024). "Several studies have revealed that IL-33 and ST2 are associated with endometriosis, which is known as a chronic inflammatory gynecological disorder." (PMID 39713054, 2024). "Remarkably, mouse model studies revealed that supplementation of recombinant IL-33 exacerbated ovarian dysfunctions and endometriosis via promoting inflammation and fibrosis within tissues." (PMID 39713054, 2024). "To evaluate the efficacy of this therapy mode, we established a mouse endometriosis model and treated the mice with IL-33-Ab and erastin." (PMID 37816731, 2023). "In the endometriosis model mice, we found that IL-33-Ab inhibited endometriosis development, and the combination of IL-33-Ab with erastin further amplified this effect." (PMID 37816731, 2023). "To verify the expression of IL-33 and ST2 (interleukin receptor-like 1), a widely accepted receptor of IL-33, in endometriosis (EMs) patients, we employed immunohistochemistry (IHC) assays on both normal endometrial (EN) and ectopic endometrial tissues (EC)." (PMID 37816731, 2023). "Knockout of IL-33 in mouse endometriosis models has led to a significant decrease in endometriotic lesion volume." (PMID 37816731, 2023). "Here, we propose a novel therapeutic approach for endometriosis that combines the ferroptosis inducer erastin and IL-33-Ab as ferroptosis immunotherapy." (PMID 37816731, 2023). "Recent studies have shown that compared to healthy females, patients with endometriosis exhibit elevated levels of interleukin-33 (IL-33) in circulation." (PMID 37816731, 2023). "By exploring the effect of IL-33-Ab and erastin on ferroptosis in endometriosis model mice, we found that they have the potential treat endometriosis." (PMID 37816731, 2023). "IL-33 levels increased the inflammatory response of endometriosis and developed the proliferation of endometrial cells mediated by group 2 innate lymphoid cells." (PMID 36362231, 2022). "Our results are consistent with several previous reports on the role of IL-33 and Tregs in endometriosis." (PMID 36428461, 2022). "IL-33 is elevated in the plasma, peritoneal fluid, and endometriotic lesions in patients with endometriosis." (PMID 36428461, 2022).
endometriosis (continued). "IL-33 perpetuates inflammation, angiogenesis, and lesion proliferation in endometriosis and promotes the invasiveness of HESCs through the ST2/MAPK/MMP-9 pathway activated by 17β-estradiol." (PMID 36428461, 2022). "The TGF-β1 and PDGF-BB produced by Tregs promote lesional growth, EMT, FMT, and fibrosis in endometriosis, while the IL-33 secreted by endometriotic cells transform Tregs into Th2-like Tregs, producing more profibrotic cytokines IL-13, IL-4, and even TGF-β1." (PMID 36428461, 2022). "Consistently, IL-33-neutralizing antibody treatment impairs the inflammatory response in endometriosis." (PMID 36362231, 2022). "In particular, they are congruent with the data that lesion-derived IL-33 exacerbates endometriosis through polarizing macrophages to the M2 subtype, since M2 macrophages also play an essential role in fibrogenesis in endometriosis." (PMID 36428461, 2022). "In particular, we provide a foundation forfurther clinical research on the immunological treatment of endometriosis, possibly by targeting IL-33 or Tregs, or any other molecules in their interactive pathways, such as TGF-β1 or ST2." (PMID 36428461, 2022). "Our results demonstrated the significantly higher serum concentration of IL-33 in the endometriosis group as compared with the healthy control group." (PMID 34754275, 2021). "The elevated serum level of IL-33 in the endometriosis patient group was attributed to myocardial damage and cardiovascular disorders." (PMID 34754275, 2021). "In conclusion, we demonstrate the presence of ST2+ ILC2s in the lesion microenvironment of patients with endometriosis and that IL-33–driven ILC2 expansion plays a vital role in the pathophysiology of endometriosis." (PMID 34699382, 2021). "To gain further mechanistic insight, we neutralized IL-33 in our syngeneic mouse model of endometriosis using AF3626, a mouse IL-33–neutralizing antibody." (PMID 34699382, 2021). "Using our murine model of endometriosis, we previously demonstrated that IL-33 likely has a pathological role in the progression of endometriosis, as it stimulated systemic inflammation and contributed to lesion proliferation." (PMID 34699382, 2021). "After inducing endometriosis, the RAG2–/– mice (ILC2 intact), RAG2–/–αCD90.2 mice (ILC2 depleted), and RAG2–/–IL-2rγ–/– mice (ILC2 deficient) were treated with PBS and IL-33." (PMID 34699382, 2021). "In particular, the alarmin IL-33 is elevated in the plasma, peritoneal fluid, and endometriotic lesions from patients with endometriosis; however, the exact role of IL-33 in the pathophysiology of endometriosis is not well understood." (PMID 34699382, 2021). "Using our well-established syngeneic murine model of endometriosis, we unravel how IL-33 and ILC2s contribute to the pathology of endometriosis." (PMID 34699382, 2021). "In this study, we used samples from patients with endometriosis to understand the spatial arrangement of IL-33 in the endometriotic lesion, and for the first time to our knowledge, we identify the presence of ILC2s in the PF from patients with endometriosis." (PMID 34699382, 2021). "Our research group and others have demonstrated that IL-33 is elevated in the peritoneal fluid (PF) and endometriotic lesion tissue of patients with deep infiltrating endometriosis and endometriomas." (PMID 34699382, 2021). "A significant difference (P < 0.001) was observed with a 77% elevation of IL-33, in patients with endometriosis." (PMID 34754275, 2021). "The elevated level of IL-33 in patients with endometriosis and its involvement in disease progression by promoting inflammation and angiogenesis have been reported." (PMID 34754275, 2021). "The peritoneal fluid and serum of endometriosis patients revealed elevated levels of IL-33 and sST2, compared to healthy women." (PMID 34754275, 2021). "As a proof of concept, we induced endometriosis in WT mice and treated them with IL-33 in addition to either a neutralizing antibody or isotype control." (PMID 34699382, 2021).